INS (insulin)
Diseases named in the same sentence as INS in open-access papers (continued):
Sharing a sentence is not in itself a finding about the gene and the disease.
Hyperglycemia (continued). "Hyperglycaemia is universal within all prediabetic and diabetic cases, and glucose-responsive expression may indicate genes and pathways important for adapting to an enhanced demand for insulin secretion." (PMID 28893192, 2017). "Thus, reported hyperglycemia may derive from an inhibitory effect of fluoride on the secretion of insulin, via altered intracellular signaling pathways related to insulin secretion." (PMID 28243943, 2017). "Hence, preventing or arresting the formation of amyloid-related β-cell failure at an early stage of T2D may preserve endogenous insulin secretion and prevent or delay hyperglycaemia." (PMID 28754022, 2017). "The mechanism for hypertension in this study is unclear and may arise from copanlisib-mediated inhibition of PI3K at the endothelial level leading to vasoconstriction, or through insulin-dependent vasoconstriction as an effect of the post-infusion hyperglycemia, or both." (PMID 27915408, 2017). "We hypothesize that the combination of HIIT with a carbohydrate-restrictive diet may be the most effective strategy to reduce hyperglycemia, improve insulin sensitivity, promote favorable changes in body composition, and preserve (or increase) endothelial function in patients with T2D." (PMID 29075629, 2017). "Since insulin treatment is one way to control the hyperglycemia, which may be the target to rescue the kidney fibrosis following IRI, insulin treatment could be expected to reduce the expression of TGF-β1 and Shh signaling and finally ameliorate the progression of renal fibrosis after IRI." (PMID 29196746, 2017). "Additionally, under IGT, adipocytes are resistant to insulin, and its effectiveness may be impaired, contributing to postprandial hyperglycemia in prediabetic states." (PMID 28635632, 2017). "Again, it can inhibit the release of insulin even among nondiabetics causing hyperglycemia." (PMID 29270319, 2017). "Interestingly, the NDF35 and NDF25 with 64.37% and 75.72% available circulating serum insulin respectively were relatively normoglycemia whereas the FDF35 with 85.75% circulating serum insulin had hyperglycaemia, which is distinctive feature seen among type 2 diabetic subjects." (PMID 28129400, 2017). "Interestingly, GPR40 stimulated insulin secretion is observed only during hyperglycemia." (PMID 28542610, 2017). "The decreased expression of antioxidative selenoprotein encoding genes might disturb the balance between oxidant and antioxidant agent and induce oxidative stress and even damage, thus impaired the pancreatic insulin secretion and function, induced hypoinsulinemia and hyperglycemia." (PMID 28763492, 2017). "In T1DM and T2DM animal models exhibiting impaired heart function when subjected to metabolic stress caused by hyperglycemia and elevated energy demand, it was shown that, unlike insulin, palmitate was able to rescue contractile function from the detrimental action of hyperglycemia." (PMID 28598967, 2017). "Our results also indicate that topical insulin application in patients with burn injury might alleviate hyperglycemia in the short term but without causing an activation of IGF1R it might be difficult to sustain its beneficial activity." (PMID 29069833, 2017). "Hence the study shows that circulating serum insulin ≥ 85.8% with overt hyperglycaemia may be utilized as the benchmark in selecting rat models for T2D studies." (PMID 28129400, 2017). "Once mass production was started, the challenge to those early pioneers of insulin treatment was learning how to use this new wonder drug, e.g., how much to give and how often to give it, in order to treat the hyperglycemia without raising the inherent risk of hypoglycemia." (PMID 28364357, 2017). "Hyperglycemia may directly affect the neural response to insulin." (PMID 28191471, 2017). "Moreover, hyperglycemia is characterized by an increase in insulin and TG levels in blood serum." (PMID 28358328, 2017).
Hyperglycemia (continued). "However, the effects of 6-month EPA treatment on postprandial hyperglycemia and hyperlipidemia, insulin secretion, and concomitant endothelial dysfunction remain unknown in patients with impaired glucose metabolism (IGM) and coronary artery disease (CAD)." (PMID 27565734, 2016). "Since in our experiment the sucrose group rats had a mild hyperglycemia, we think that, as others have suggested, miR-146a upregulation through EVs may be an anti-inflammatory mechanism important in the controls of insulin sensitivity induced by inflammatory mediators." (PMID 27999792, 2016). "However, aging β-cells may eventually fail to adapt to increasing demands for insulin production, which manifests in hyperglycaemia and T2D1." (PMID 27029739, 2016). "Unlike SQ Lispro insulin, SQ regular insulin did not cause “rebound hyperglycemia” at higher doses." (PMID 26819233, 2016). "Thus, knockout of Irs1 in the PP zone impaired the insulin action of suppressing gluconeogenesis, resulting in marked hyperglycaemia, and knockout of Irs1 in the PV zone impaired the insulin action of stimulating lipid synthesis and storage, preventing steatosis." (PMID 27708333, 2016). "DM2 is a metabolic disorder characterized by hyperglycemia, which may be due to a defect in insulin secretion of pancreatic β cells, insulin resistance in peripheral tissues, and/or an excessive accumulation of triglycerides and fatty acid derivatives in skeletal muscles." (PMID 27313601, 2016). "Thus, we speculate that the stress-induced hyperglycaemia results from a higher corticosterone response to stress in combination with limited availability of insulin." (PMID 27069934, 2016). "However, in spite of the hyperglycaemia, circulating insulin levels were lower the first 2 months of HF diet intake, probably because of the lower carbohydrate content of the diet, as it has been previously shown that low-carbohydrate/HF diets generate hypoinsulinemia." (PMID 27885970, 2016). "However, even if insulin is quantitatively decreased in PPARγ-/F:MORE+/Cre pancreas this is unlikely to fully explain the inappropriately normal levels of circulating insulin observed in the presence of extreme hyperglycemia." (PMID 27505464, 2016). "Typically, hyperglycemia is less severe in ob/ob mice and in leptin receptor-deficient mice on the C57BL/6J background, whereas db/db mice on the C57BLKS background develop fulminant diabetes and require exogenous insulin administration in order to maintain well-being beyond 24 weeks of age." (PMID 26814757, 2016). "Liver is a relevant organ to assess the impact of insulin and glucagon deficiency because re-expression of the glucagon receptor in the liver of STZ-treated Gcgr-/- mice, and conditional inactivation of the insulin receptor in hepatocytes are both sufficient to trigger hyperglycemia." (PMID 27092792, 2016). "Nevertheless, the hyperglycemia in combination with the inhibited insulin secretion in response to afferent VNS in our study may justify investigating the effects of VNS on glucose metabolism in patients receiving VNS therapy which – to our knowledge – has not been investigated so far." (PMID 26884478, 2016). "Therefore, MAP3K1 is a member of MAPK signal transduction in response to stress stimuli of hyperglycemia, and genomic variation at this gene may have important roles in beta cell death and insulin resistance and inflammatory cytokine secretion." (PMID 27942499, 2016). "However, reduced insulin secretion is mainly responsible for the clinical picture of hyperglycemia." (PMID 27471550, 2016). "Together, these findings indicate that although glucagon signaling blockade does not prevent hyperglycemia in diabetic mice that exhibit extreme insulin deficiency, it results in enhanced formation of new insulin-producing cells by increasing the absolute number of converting α-cells." (PMID 27092792, 2016). "Post-pancreatectomy hyperglycemia may require either temporary or permanent insulin treatment." (PMID 26758964, 2016).
Hyperglycemia (continued). "On the basis of these findings, we hypothesized that under the HF condition where the expression of Irs2 is downregulated, deletion of Irs1 leads to impaired insulin signalling in both the PP and PV zones, resulting in hyperglycaemia and suppression of steatosis." (PMID 27708333, 2016). "While most studies have used glucose-insulin-potassium (GIK) as insulin treatment, in this study we used hyperinsulinemic euglycemic clamping for this purpose because maintenance of euglycemia eliminates the possible effects of hypo- and hyperglycemia on myocardial perfusion and function itself." (PMID 27651131, 2016). "Moreover, hypovitaminosis D leads to defective insulin secretion, reduced glucose homeostasis, and increased risk of T2DM in all age bands, whereas increased pancreatic islet RAS activity in hyperglycemia impairs islet function and survival under hyperglycemic conditions." (PMID 26959059, 2016). "Although the mechanism of hyperglycemia induced by scorpions’ venom is not clearly understood, there are studies demonstrating that it can occur through the excessive release of catecholamine, increases in glucagon and cortisol, and alterations in thyroid hormone levels or insulin secretion." (PMID 27660634, 2016). "In addition, insulin, but also triglycerides and in some studies hyperglycemia, could increase the expression of PAI-1 by human arterial segments in vitro, both in normal vasculature and within atherosclerotic plaques." (PMID 26089884, 2015). "However, since LV diastolic function may already be impaired in the pre-diabetic or even preclinical phase of glucometabolic disturbances, i.e. before the onset of sustained hyperglycemia, an independent mechanistic role of insulin resistance may exist." (PMID 26655187, 2015). "Usually, in studies of diabetic atherosclerotic pigs, long-term sustained hyperglycemia is applied to accelerate the atherosclerosis, potentially leading to adverse effects including wasting or deleterious non-thriving of the animals, unless blood glucose is controlled by exogenous insulin." (PMID 26394837, 2015). "Key to successful management of hyperglycemia is regular communication between the members of the care team as well as anticipating and rapidly implementing a new treatment paradigm in response to changes in immunosuppression, nutrition, renal function, or evidence of changing insulin resistance." (PMID 25721247, 2015). "In addition, postprandial insulin secretion slows down mitochondrial fat oxidation by inhibiting carnitine palmitoyltransferase (CPT1) activity due to increased malonyl-CoA concentrations present during hyperglycemia." (PMID 26076487, 2015). "Importantly, these gut-derived insulin-producing cells were characterized by expression of β-cell maturity factors, glucose-stimulated insulin release in-vitro and were capable of reversing hyperglycemia following STZ administration in mice." (PMID 25841258, 2015). "However, in people with type 1 diabetes, this increase in plasma glucagon in the absence of sufficient insulin has been shown to cause postprandial hyperglycaemia." (PMID 26202844, 2015). "Therefore, the mild hyperglycemia in pinealectomized hamsters in long days may be, as observed in rats, due to a reduced responsiveness of the target cells to insulin." (PMID 26074760, 2015). "The available clinical data suggest that prevention of severe hyperglycemia may reduce cell damage; however, preventing hyperglycemia by using high doses of insulin, as required in cases of high intake of carbohydrates, can blunt the early inflammatory response." (PMID 25886997, 2015). "Moreover, Aloe vera leaves extract has also demonstrated hypoglycemic effect in both T1DM and T2DM rats, and the quercetin-rich onion peel extract had shown to improve hyperglycaemia and insulin sensitivity by upregulation of insulin receptor and glucose transporter 4 mRNA expressions." (PMID 25883984, 2015).
Hyperglycemia (continued). "Since our model could be hyperinsulinemic due to prolonged state of hyperglycemia, as previously reported, the alterations of Gata3 (Th2) and Foxp3 (Treg) expression found in the present study could be indirectly induced through an insulin-dependent pathway." (PMID 26207186, 2015). "Earlier studies showed acute hyperglycemia after a glucose load resulted in change of the amino acids profiles in healthy adults, obese individuals and impaired glucose tolerance individuals because the metabolism in the body was regulated by the postprandial level of insulin." (PMID 26184292, 2015). "Kamalakkannan and Stanley (2006), studying the action of rutin in diabetic rats verified a decrease in the oxidative stress (liver, kidney and brain), supporting the hypothesis of pancreatic β cell protection, i.e., improvement in insulin secretion and decrease in hyperglycemia." (PMID 26783951, 2015). "Thus, following a meal rich in carbohydrates, controlling blood glucose at the ideal levels becomes difficult as the body is rendered less capable of responding to released insulin, which results in the accumulation of glucose in the blood, leading to postprandial hyperglycemia." (PMID 26308046, 2015). "Whether this is due to a clinically important increase in hypoglycaemia with insulin or because hyperglycaemia is an epiphenomenon rather than a mediator of a poor outcome, these discrepancies indicate a need to look beyond the hyperglycaemia itself and explore the related pathophysiology." (PMID 26567860, 2015). "According to this mechanism, increased supply of plasma TG per se could constitute a source of increased fatty acid availability and oxidation that can impair insulin action and hence, glucose metabolism and utilization that leads to development of hyperglycemia." (PMID 25593725, 2014). "In addition, increased gluconeogenesis in insulin-resistant state further enhances hyperglycemia." (PMID 25106484, 2014). "Coreopsis tinctoria Nutt.have been used traditionally in Portugal to control hyperglycaemia and a study revealed that daily administration of Coreopsis tinctoria Nutt promoted the recovery of glucose tolerance by inhibition of glucose absorption and direct promotion of insulin secretion." (PMID 25512113, 2014). "Importantly, these tissue-damaging effects of hyperglycemia are particularly noticeable in endothelial cells, since they retain expression of non-insulin-dependent GLUTs allowing intracellular glucose to rise concomitantly with extracellular glucose concentrations." (PMID 25143800, 2014). "Finally, it might be inferred that the stress-induced protein which has been reported to cause life-threatening diseases like hypertension, hyperglycemia, and AIHD could be controlled by insulin." (PMID 24649391, 2014). "Accordingly, a reduction in insulin sensitivity in the hypothalamus might lead to the diminished efficiency of this hormone in blocking glucose formation, which might contribute to the hyperglycemia of diabetic patients." (PMID 25346723, 2014). "In addition to structural, cellular and hormonal conservation of the chondrichthyan pancreas compared to other vertebrates, there is also a conservation of function, with glucose-sensitive insulin release, pancreatectomy-induced hyperglycemia and exogenous insulin-induced hypoglycaemic effects." (PMID 25480530, 2014). "Interestingly, Ras/Src-transformed tumors in a drosophila model of diet induced hyperglycemia and insulin resistance retained insulin sensitivity and displayed aggressive behavior toward increased metastases by increasing insulin receptor expression and preferential glucose uptake." (PMID 25526027, 2014). "Therefore, hyperglycemia caused by chronic exposure to excess insulin is not likely to be due to hypoglycemia-induced effects as suggested by Somogyi." (PMID 24741073, 2014).
Hyperglycemia (continued). "Through the application of insulin therapy at the initial stages of T2D mellitus to improve the control of plasma glucose levels, it may be possible to reverse the damage on β cells, which results from hyperglycemia." (PMID 24944613, 2014). "Therefore, a low phosphorylation of FOX01 in preterm infants may play a role in their high incidence of hyperglycemia; whether these differences persist under insulin‐stimulated conditions remains to be determined." (PMID 25524279, 2014). "Therefore hyperglycemia/hyperlipidemia-induced islet IL-1 activity promotes cytokine/chemokine expression, leading to recruitment of innate inflammatory cells, which alter both functional β-cell mass and insulin sensitivity." (PMID 24587207, 2014). "Moreover, in several in vitro studies, researchers have shown that endozepines inhibit glucose-stimulated release of insulin in rats, suggesting that an increase of endozepine levels could contribute to hyperglycemia induced by inflammation." (PMID 25407756, 2014). "Moreover, fasting glucose and 2-hour glucose appear to reflect different underlying biomedical mechanisms, with 2-hour glucose largely influenced by peripheral insulin resistance, and both measures detect hyperglycaemia in different groups of individuals to some extent." (PMID 24599391, 2014). "Insulin may have a confounding effect on stroke outcome and poststroke hyperglycemia." (PMID 24747428, 2014). "Therefore, we conclude that regulation of miR-29-MCL-1 axis by insulin is a cardioprotective mechanism and compensatory hyperinsulinemia in conditions of hyperglycemia would regulate miR-29-MCL-1 axis in diabetic heart and prevent significant myocardial damage in young (11- and 15-week) ZDF rats." (PMID 25062042, 2014). "Similarly, when comparing nateglinide and acarbose to target postprandial hyperglycaemia in new-onset, non-insulin requiring individuals with diabetes, improvement of post-meal flow-mediated dilatation was noted with an edge of acarbose over nateglinde (as to the acarbose studies see further down)." (PMID 24742256, 2014). "The mechanism for the observed accelerated metabolic changes induced by insufficient insulin administration in the presence of hyperglycemia may originate from the cellular uptake of glucose, which is mediated by glucose transporters (GLUTs) with distinct tissue‐specific expressions." (PMID 25501426, 2014). "Although cytokine products and reactive oxygen species produced by innate immune cells may have profound effects on glucose disposal and utilization in the periphery as well as on insulin production by the pancreas, we only focus on the effects of hyperglycemia and insulin on innate immune cells." (PMID 24899891, 2014). "Furthermore, the reduction of insulin sensitivity in the state of hypertriglyceridemia may lead to the formation of hyperglycemia." (PMID 25045660, 2014). "Thus, loss of insulin signaling and hyperglycemia rather than toxic effects contributed to persistent liver cell injury." (PMID 23828575, 2013). "Also, the exact treatment of hyperglycemia with insulin keep proteinuria in the same level or even reduce its value, although this beneficial effect may be apparent after two years of strict control of blood glucose." (PMID 25340133, 2013). "However, the amount of insulin was insufficient to correct postprandial hyperglycemia." (PMID 23826312, 2013). "Thus, reducing hepatic gluconeogenesis and enhancing hepatic insulin sensitivity may meliorate hyperglycemia." (PMID 24086476, 2013). "The studies above clearly indicate that at least in some cases a direct effect of impaired insulin signaling, but not hyperglycemia, may serve as a pathogenic substrate for hyperactivity of deep muscle nociceptors." (PMID 24303103, 2013). "Furthermore, these derived IPCs could secrete insulin in a glucose-dependent manner in vitro, and could alleviate the hyperglycemia of STZ-induced diabetic rats when transplanted under the renal capsule." (PMID 24058711, 2013).